MMP14 (matrix metallopeptidase 14)
Diseases named in the same sentence as MMP14 in open-access papers (continued):
Sharing a sentence is not in itself a finding about the gene and the disease.
tumor (continued). "Considering the high CR of MMP14 at the TSI at primary and ENE sites, the MMP14 co-scoring system could predict tumour invasiveness at the ENE site by assessing it at the primary TSI." (PMID 36765296, 2023). "As we identified ADAM10 as a key protease to induce CD44 dependent transcriptional upregulation of MMP14 and MMP2, inhibition of CD44 cleavage by ADAM10 might be a future translational approach to prevent tumor cell migration and invasion." (PMID 36876041, 2023). "MMP14 expression increased γδ T-cell migration speed exclusively in the tumor stroma and not inside the tumor tissue, supporting the functional role of MMP14 in cleaving the peritumoral ECM." (PMID 37139603, 2023). "In addition, an IHC assay with the transplanted tumours indicated high expression of p-SMAD3, MMP2, MMP9 and MMP14 in the control group." (PMID 37689715, 2023). "SPP1+ macrophages from tumor tissues showed high expression of MMP9, MMP12, MMP14, and MMP19, which could contribute to the degradation of the basement membrane for the invasion of tumor cells." (PMID 38347955, 2023). "CMFDA-labeled nontransduced γδ T cells or γδ T cells expressing MMP14 were plated on top of unfixed xenograft-derived tumor slices and were microscopically monitored." (PMID 37139603, 2023). "Several matrix metalloproteinases (MMPs) were up-regulated in tumour samples, namely MMP12 (5.1-fold), MMP14 (2.3-fold) and MMP2 (2.2-fold), which cleave elastin (and insulin), collagen (and other extracellular proteins, such as aggrecan) and certain collagens (and gelatin), respectively." (PMID 37397358, 2023). "However, soluble NKG2D ligands generated by a disintegrin and metalloproteinase 10 (ADAM10), ADAM17, and matrix metalloproteinase 14 (MMP14), can promote NKG2D down-regulation, impairing NK cell-effector functions and facilitating tumor immune escape." (PMID 37601668, 2023). "Nondigested pro-IL-12 showed 10-fold less activity than MMP14-digested pro-IL-12 in vitro, yet injection of pro-IL-12 achieved tumor suppression and reduced adverse effects in mice." (PMID 36797799, 2023). "However, the growth and lymph node metastasis of MMP14 o.e./CTNNA1 KO cells were reduced compared to the MMP14 o.e. cells, indicating that the tumour promoting effect of elevated MMP14 levels depends on cell-cell adhesion." (PMID 36892272, 2023). "Additionally, the expressions of ECT2, FGD6, MMP14, and SLC2A1 were related to the staging of the tumor." (PMID 37604837, 2023). "Indeed, tumor cells attenuate the immune anti-tumoral action by MMP-2, MMP-9, MMP-13, and MMP-14 secretion, leading to T-cell activity hindrance." (PMID 35572966, 2022). "A decrease in miR-584-5p could be seen in the tumor tissues of patients with NSCLC and cell lines under MMP-14 regulation or YKT6 targeting." (PMID 36147635, 2022). "The tumor sections with the first antibody anti-MMP-14 omitted and incubated with PBS (negative control) did not exhibit positive staining." (PMID 36518899, 2022). "Moreover, the results showed that the expression levels of LOXL2, PLOD2, MMP14 and SPOCK1 was higher whereas that of DCN was lower in tumor tissues compared with normal tissues." (PMID 36186418, 2022). "Moreover, the patient subset with both a high MMP14+ CAF/CAF ratio and a low tumor-infiltrating lymphocyte density showed the worst prognosis." (PMID 36052235, 2022). "Moreover, the mRNA expression of MMP14 and INHBA was significantly up‐regulated compared with non‐tumour samples in the Oncomine Pei pancreas cohort." (PMID 35150061, 2022). "It has been proposed that a matrix metalloproteinase 14 (MMP14)-activatable NIR-II nanoprobe (A&MMP@Ag2S-AF7P) can be used to distinguish the NB tumor tissues from surrounding non-cancerous tissue." (PMID 35721107, 2022). "Also, in melanoma, PI3K activation triggered by VEGF-A/VEGF-R1 binding contributes to VM by stimulating MMP-14-mediated MMP-2 activation and subsequent tumour cell migration and tube formation." (PMID 36224457, 2022).
tumor (continued). "Interestingly, we observed in tumor samples higher levels of MMP-2 and MMP-9, along with lower levels of MMP-14, their main activator." (PMID 36518899, 2022). "Important for (tumor) angiogenesis, but not for vasculogenesis, MMP-14 acts as an endogenous suppressor in lymphangiogenesis by shedding LYVE-1 and inhibiting NF-κB-mediated VEGF-C production by macrophages." (PMID 35008569, 2021). "Secondly, the expression of MMP14 at protein levels in tumor specimens was not further demonstrated, which was needed to be further demonstrated." (PMID 34868395, 2021). "Tumor grafting experiments with B16F1 cells, which were injected intradermally into the flank of MMP14Sf−/− and control mice, showed reduced tumor growth in the absence of fibroblast-MMP14 as compared to controls." (PMID 34830157, 2021). "If a given tumour is MMP-14 positive irrespective of its histological type, targeted treatment can be administered after debulking with chemotherapy and surgery if necessary and hopefully lead to prolonged responses to treatment." (PMID 34344453, 2021). "However, other studies report that miR-150-5p inhibits Wnt-β-catenin signaling via targeting GSKIP and HMGA2, or suppresses MMP14, or GLUT1 to exert its tumor-suppressive properties in NSCLC." (PMID 34193018, 2021). "CAFs may also be involved in tumor escapes from the immune response by releasing MMP-2, MMP-9 and MMP-14." (PMID 34204372, 2021). "Of the malignant tumours, only one was negative for tumour cells and stroma, and 18/19 showed MMP-14 mRNA expression in the stroma, of which 8/19 also showed expression in the epithelium." (PMID 34344453, 2021). "Indeed, both iRP-D26 and iRP-D28A showed upregulation of several genes known to facilitate human EVT and/or tumor cell invasion, including SDC2, TIMP3, MMP14, and ADAM12." (PMID 34154587, 2021). "MMP14 activity also triggers the proteolytic processing and activation of Heparin-Binding EGF-like growth factor (HB-EGF), which stimulates the EGFR signaling pathway and increases tumor proliferation and growth." (PMID 34976811, 2021). "MMP14 sustains cancer cell trafficking through the extracellular matrix ECM, and strengthens BCSC ability in anchorage-independent growth, tumor initiation, invasion, and migration under hypoxic nutrient-deprived conditions." (PMID 34195201, 2021). "To explore the anti-tumor effect of ProIFN, we first determined the expression levels of tumor-enriched enzymes such as MMP-2, MMP-9, MMP-11, MMP-14, fibroblast activation protein alpha (FAP), and urokinase plasminogen activator (uPA) in a variety of tumor lines." (PMID 34620867, 2021). "MMP-14 also contributes to the degradation of the extracellular matrix by activating other MMPs, such as pro-MMP-13 and pro-MMP-2, and plays a crucial role in molecular carcinogenesis and tumor growth." (PMID 33946534, 2021). "Notably, ARL4C and MMP14 were expressed more highly in invasive cancer cells rather than in PanIN lesions, although IQGAP1 was thoroughly expressed in tumor lesions including PanIN area." (PMID 34590580, 2021). "In addition, matrix metalloprotease 14 (MMP14) promotes shedding of MHC class I Chain related molecule A (MICA), thus impairing NK and T cell anti-tumor responses." (PMID 34150958, 2021). "The MMP-14-cleavable substrates comprise fibril-forming collagen types I, II and III and other ECM proteins, in particular BM laminins and laminin-332 ectopically expressed in the tumor stroma." (PMID 33379400, 2020). "Our results revealed that MMP14 is significantly overexpressed in tumor tissues compared to non-tumor tissues, and high MMP14 expression is significantly correlated with poor overall survival (P = 0.019)." (PMID 33363004, 2020). "Expression of matrix metalloproteases 2, 9 and 14 (MMP-2, MMP-9, MMP-14), tissue inhibitors of metalloprotease 1 and 2 (TIMP-1, TIMP-2) and vascular endothelial growth factor A (VEGF-A) is involved in tumor invasion and metastasis via extracellular matrix degradation and angiogenesis." (PMID 32669083, 2020).
tumor (continued). "Consequently, MMP-14 decisively controls collagen turnover and the breaking of ECM barriers in tumor progression." (PMID 33379400, 2020). "Conversely, MMP14 expressed by NSCLC cancer cells and myeloid cells in the tumor microenvironment digests the heparin-binding EGF-like growth factor (HB-EGF) to generate both soluble and membrane-bound heparin-independent growth factors that can activate EGFR signaling." (PMID 33014869, 2020). "MMP-14 mediates tumour invasion and angiogenesis and PEDF may reduce tumour cell metastatic potential by negatively regulating MMP-14, and subsequent MMP-2 activation in various cancer types, including BC." (PMID 33238558, 2020). "They further demonstrated that hypoxia-induced recruitment of α6β4 integrin toward exosomal C4.4A, MMP-14 membrane type 1 matrix metalloproteinase/MT1-MMP), and TACE (tumor necrosis factor-α-converting enzyme) allows for a shift from adhesion to motility of recipient tumor cells." (PMID 30925935, 2019). "Hence we validated gene expression of MMP1, MMP3, MMP11, MMP13, MMP14, ADAMTS1 and ADAMTS5 genes belonging to metallopeptidase activity, using qPCR in 67 tumours." (PMID 31292488, 2019). "In summary, the infusion of CAR-147 macrophages can degrade the dense collagen-based matrix that surrounds tumours, which may require the involvement of MMP3, MMP14 and MMP15." (PMID 31570753, 2019). "MMPs are a family of zinc-dependent matrix-degrading proteases that have a crucial role in tumor metastasis, in which MMP2, MMP9, and MMP14 are the three major proteinases among MMP subfamily members involved in pericellular proteolysis associated with cell migration." (PMID 31093311, 2019). "For example, while MMP-14 degrades collagens I, II and III, fibronectin, laminin, aggrecan and tenascin, and hence can clearly reduce physical barriers to tumor growth and metastatic spread, it is also a transmembrane protein capable of intracellular signaling." (PMID 30034628, 2018). "Then we analyzed the protein levels of those tumor-related genes, and found that both β3GnT8 and β3GnT2 could markedly elevate MMP2 and MMP14 expression." (PMID 29875690, 2018). "Indeed, mRNA expression of human MMP-2, MMP-9 and MMP-14 (MT1-MMP) was upregulated by PTX treatment and MT1-MMP protein became abundant in E-cadherin- mesenchymal tumor cells." (PMID 29507310, 2018). "Furthermore, immunofluorescent staining of tumor cryosections with anti-CA9, a hypoxia marker, revealed that MMP-14 blockade reduced hypoxia in 4T1 tumors." (PMID 28938563, 2017). "Finally, we focused on the MMP14 gene, which was found to be up-regulated in EMT and contribute to tumor cell invasion." (PMID 28977854, 2017). "In addition, several studies have reported that the secretion or expression of MMPs by tumor cells (including the secreted MMP-2, MMP-9 and the membrane type MMP-14) can lead to the shedding of MICA/B at their surface." (PMID 28423623, 2017). "Invadopodia concentrate proteases such as MMP14, MMP9 and MMP2 for local directed release during extracellular matrix breakdown, and along with cortactin and Tks5, have now been shown to be required for tumor cell extravasation during metastasis." (PMID 28692057, 2017). "Matrix metalloproteinase 14 (MMP-14), also known as membrane type-1 MMP, plays a pivotal role in digesting the extracellular matrice (ECM) and activating MMP-2, thereby promoting tumor invasion and metastasis." (PMID 28827574, 2017). "MMP14 can cleave a variety of substrates, including cell surface proteins (such as CD44) and other MMPs (such as pro-MMP2 and pro-MMP13), and induce ECM degradation and tumor cell invasion by increasing the secretion of other MMPs." (PMID 27564100, 2016). "Matrix metalloproteinase 14 (MMP-14), also known as membrane type-1 matrix metalloproteinase, is able to degrade various extracellular matrix (ECM) components and facilitate the tumor cells to remodel and penetrate the ECM." (PMID 26084291, 2015).
tumor (continued). "MMP14 is a ‘master switch' proteinase with a C-terminal sequence that acts as membrane-anchoring domain, and is a key enzyme involved in ECM degradation and invasion of tumor cells." (PMID 26610210, 2015). "Recently, it has been hypothesized that MMP-14 also has a role in promoting VEGF secretion and can activate tumor angiogenesis." (PMID 24765144, 2014). "Tumor invasion can be induced by macrophages through the production of enzymes and inhibitors that regulate the digestion of the ECM, as well as through the production of several MMPs including MMP-1, MMP-2, MMP-7, MMP-9, MMP-12 and MMP-14." (PMID 24578639, 2014). "The results indicated that the upregulation of β-catenin and MMP14 the knockdown of DKK1 may result in the elevated activation of the Wnt signaling pathway and downstream signaling events involved in tumor migration and invasion." (PMID 24137406, 2013). "We presumed that the downregulation of MMP-2, MMP-9 and MMP-14 might alleviate the extracellular matrix (ECM) degradation, thus maintaining the vascular basement membrane and normalizing tumor vasculature." (PMID 22496834, 2012). "MT1-MMP (or MMP14) is widely expressed by multiple cell types within the tumour microenvironment, including endothelial cells, fibroblasts and in some instances tumour cells." (PMID 22363483, 2012). "The results indicated that the ratios between MMP-2/RECK, MMP-9/RECK and MMP-14/RECK were significantly higher in the tumor than in adjacent non-tumor tissue samples (p = 0.0024, p = 0.0001 and p < 0.0001, respectively)." (PMID 19144199, 2009). "The process strictly connects MT-MMP and MMP functions, and it has been shown that MMP14 is essential for proMMP-2 activation: pro-MMP-2 activation by MMP14/TIMP complex is realized in an environment of low TIMP concentration; furthermore TIMP 4 over-expression can reduce tumour invasiveness." (PMID 19753302, 2009). "In our study, when each factor was taken separately, and after adjustment for clinical prognostic factors, only MMP-14 was a significant factor of survival, suggesting that MMP-14 may be one of the key steps in tumor invasion and metastasis." (PMID 16776850, 2006). "Furthermore, cells in the myCAF-(F-POSTN) and iCAF-(F-ALPL) groups expressed high levels of matrix metalloproteinases (MMPs; e.g., MMP2, MMP14, MMP23B, and MMP19), indicating that these cells are involved in degradation of the basement membrane and ECM to facilitate tumor metastasis." (PMID 40319103, 2025). "A mechanistic study revealed that GSDMD was involved in regulating OSCC metastasis through a novel mechanism involving interactions with MMP14 to upregulate MMP14 expression, thereby mediating the tumor EMT process and inducing OSCC metastasis without activating the classical pyroptosis process." (PMID 40178046, 2025). "Furthermore, the activities of MMP-14 and MMP-15 in the cells of both tumor grades were determined." (PMID 39125675, 2024). "To test whether inhibiting PMN tumor infiltration or TAN proangiogenic activity can be used as therapy to curb tumor growth, we utilized commercially available small molecule inhibitors Reparixin (a CXCR2 inhibitor) and NSC405020 (allosteric MMP14 inhibitor)." (PMID 38329810, 2024). "Interestingly, while MMP14i increased tumor Collagen I levels, it did not significantly impact the levels of Laminin-1, suggesting a lower MMP14 affinity toward Laminin-1 and/or reduced TAN accessibility to Laminin-rich regions, such as the tumor basement membrane." (PMID 38329810, 2024). "Moreover, MMP14 expression in tumour nests was a reliable predictor in small specimens without connective tissues." (PMID 36765296, 2023). "In addition, neither treatment with γδ T cells nor with γδ T cells expressing MMP14 increased tumor cell invasion or metastasis when compared with vehicle-treated animals." (PMID 37139603, 2023).
tumor (continued). "In vivo studies have revealed that MMP14 in the TME creates a suitable primary and pre-metastatic niche in the LN for tumour survival during epithelial–mesenchymal transition (EMT), which may be attributable for the similar expression profiles of MMP14 at TSI and ENE sites." (PMID 36765296, 2023). "Tumor necrosis is functionally mediated by infiltrating monocytes/macrophages, and it has been demonstrated that the mobilization of monocytic myeloid-derived suppressor cells (MDSCs) promotes tumor recurrence after liver transplantation via CXCL10/TLR4/MMP14 signaling." (PMID 36698095, 2023). "Furthermore, CD44 could specifically interact with the PEX sequence of MMP14, activate MMP2, and regulate cell migration, suggesting that CD44 and MMP2 may be closely related to the tumor metastasis." (PMID 36192574, 2023). "In this study, we found that SUCNR1, C3aR1, C5aR1, MMP14, THBS 1, TSP-1, and TREM2, which are abnormally expressed in tumor tissue in situ, may be potentially associated with lymph node metastasis." (PMID 37744272, 2023). "MMP-14-specific Fabs were also identified using phage-displayed synthetic humanized Fab library against the extracellular domain of MMP-14, and among them, Fab 3369, which inhibits the catalytic domain of MMP-14, demonstrated anti-tumor activities in vitro and in vivo." (PMID 36741729, 2022). "A higher percentage of MMP14-expressing cells among CAFs (MMP14+ CAF/CAF ratio) was associated with a poorer RFS (HR of 1.936, with a 95% CI of 0.855–4.384), whereas a similar trend was not apparent for MMP14 expression in tumor cells, TAMs, or TILs." (PMID 36052235, 2022). "Representative tumor slices were analyzed by using Matrix-Assisted Laser Desorption/Ionization (MALDI) and stained for H&E as well as putative stem-like cell markers and invasion markers (Nestin, MMP14, Musashi 1, CD44) in order to establish the basis for a biologically-derived CTV definition." (PMID 36230481, 2022). "However, there has been no study on the effect of MMP14 on the immune infiltration and prognosis of pan tumor cells, which needs to be addressed." (PMID 34604053, 2021). "Thirdly, the tumor-related function of MMP14 was not explored using in vitro and vivo assays." (PMID 34868395, 2021). "Remarkably, ER-localization of GALNTs in the GALA pathway induces O-Glycosylation of the matrix metalloprotease MMP14 and ER-resident Calnexin, thus drives MMP14 activation and Calnexin/ERp57 cell surface distribution, respectively, both of which promote ECM degradation and tumor development." (PMID 34055798, 2021). "Similarly, gene expression of EPHA2, KDR, LAMC2, MMP1, and MMP14 did not vary between tumours of mice treated without and with aspirin." (PMID 32246008, 2020). "It has been reported that MMP-14 could inhibit tumor angiogenesis by mediating the shedding of endoglin, thereby exerting a negative effect on tumor progression." (PMID 31956360, 2020). "Although MMP14 may be overexpressed in PDAC, MMP14 does not correlate with clinical characteristics such as tumor differentiation, tumor size, lymph node status, or patient survival." (PMID 32325664, 2020). "We could see that about half MMPs are highly expressed in tumor tissues as compared with normal tissues, including MMP9, MMP10, MMP11, MMP12, MMP15, MMP25, MMP26 (all, P<0.05), while some other MMPs decreased in tumor tissues, including MMP2, MMP14, MMP16, MMP24, MMP28(all, P<0.05)." (PMID 32669958, 2020). "A possible explanation for this discrepancy might be that these observations were based on limited material of a tissue array and that the numbers of MMP14-expressing tumor cells were not determined separately." (PMID 32872536, 2020). "MMP-14 is well known to be important in invasion, but we did not know whether tumor stem cells expressed MMP-14." (PMID 30034628, 2018).